IDH1 (isocitrate dehydrogenase (NADP(+)) 1)
Diseases named in the same sentence as IDH1 in open-access papers (continued):
Sharing a sentence is not in itself a finding about the gene and the disease.
astrocytomas (continued). "DRG2 was reported to be significantly under expressed in IDH1-mutant astrocytoma, which are frequently ATRX-mutant/ALT-positive." (PMID 39921567, 2025). "These tumors are histologically high-grade IDH1 mutant astrocytomas and exhibit hypermutant genotype and microsatellite instability." (PMID 40949165, 2025). "The latest version of the WHO classification has distinguished IDH1-mutant GBMs as a distinct diagnosis called astrocytoma WHO grade IV, IDH1 mutant." (PMID 40996961, 2025). "Focal amplifications in particular did not drive cluster segregation but tended to enrich amongst higher grade IDH1/2-mutant astrocytoma cases within each cluster." (PMID 39584448, 2025). "We refine the molecular criteria for IDH1/2-mutant astrocytoma by augmenting histologic grade with hemizygous CDKN2A/B deletion and focal gene amplifications to establish three prognostically distinct tiers." (PMID 39584448, 2025). "We identified 998 unique adult patients with IDH1/2-mutant astrocytoma from three datasets: DFCI (n = 336), GENIE (n = 398), and TCGA (n = 264)." (PMID 39584448, 2025). "To analyze tumor grade-specific differences in matrisome gene expression, we performed parallel spatial transcript mapping of a grade III astrocytoma sample (IDH1 R132H)." (PMID 41366031, 2025). "In this context, we present a unique case of an IDH-1-R132H-mutant grade 4 astrocytoma with a PNET-like component that developed biopsy-proven extraneural metastases." (PMID 41029737, 2025). "By contrast, IDH1/2-mutant astrocytomas had a broader range of cooccurring deleterious alterations across various pathways, including between CDKN2A/B and EGFR." (PMID 39164213, 2025). "In IDH-wt astrocytoma IDH1/2-wt, treatment according to Stupp- or CeTeG protocol resulted in similar PFS and OS compared to those treated with radiotherapy followed by sequential chemotherapy (p = 0.1134)." (PMID 41466163, 2025). "Mutations in the isocitrate dehydrogenase (IDH) genes (IDH1/IDH2) are a critical marker in these tumors, with IDH-mutant astrocytomas generally exhibiting a more favorable prognosis compared to their IDH-wildtype counterparts." (PMID 41007735, 2025). "A peptide vaccine directed against IDH1 R132H was developed and tested in a Phase 1 trial, where it was given to patients with grade 3–4 astrocytoma either after radiotherapy or in conjunction with adjuvant temozolomide." (PMID 40867259, 2025). "Specifically, the label defined its indication for patients with IDH1- or IDH2-mutant astrocytoma or oligodendroglioma following surgery." (PMID 40867259, 2025). "Ten patients were initially diagnosed with Isocitrate Dehydrogenase-1 (IDH-1)-mutant glioblastoma and would now be considered IDH-mutated astrocytoma WHO-grade 4." (PMID 39518091, 2024). "In presence of a consistent morphology, it is necessary to exclude a IDH1/IDH2 mutation and thus the diagnoses of an IDH-mutant astrocytoma or IDH-mutant, 1p/19q-codeleted oligodendroglioma." (PMID 37658995, 2024). "More specifically, the highest number of patients with IDH1 mutation in tissue was found in the astrocytoma grade (G) III (38.1%), following by astrocytoma G II (23.8%), oligodendroglioma (14.3%), astrocytoma G IV (9.5%), and oligoastrocytoma (9.5%)." (PMID 38172718, 2024).
astrocytomas (continued). "It would be of interest to investigate the association between older patients and increased odds of MGMT methylation, in IDH1 mutant astrocytomas." (PMID 39767640, 2024). "Among grade 2 and 3 astrocytomas, a few cases showed IDH1 negativity (42.1% and 33.3%, respectively), and a few of them showed retained ATRX (78.9% and 66.7%, respectively)." (PMID 39192927, 2024). "Mutations in genes coding for IDH1 or IDH2 (isocitrate dehydrogenases) occur frequently in oligodendroglioma WHO grades 2, 3 and astrocytoma grades 2, 3, 4 resulting in global changes in DNA methylation." (PMID 38711090, 2024). "The most notable finding was a WHO grade IV diffuse astrocytoma with the IDH1 R132 mutation in the right parietal basal ganglia region pathology, which differed from the WHO grade II astrocytoma, IDH-NOS found in the right frontal lobe lesion." (PMID 38919539, 2024). "Nine patients completed the protocol, and three of them were in a progression-free stage at 80, 64, and 62 months since diagnosis (all young, two of them with the IDH-1 mutation and one with a Grade III astrocytoma)." (PMID 39338183, 2024). "Out of 29 patients (21.3%) with IDH mutation, 28 patients (20.6%) had IDH1 mutations, and 1 patient (0.7%) had IDH2 mutations; they were diagnosed with CNS WHO grade 4 astrocytoma, IDH-mutant, instead of glioblastoma." (PMID 39457569, 2024). "Lastly, we found that RSL3 depletes the “N1IC_up” gene signature in all patient samples except for the IDH1-mutant astrocytoma, an effect which is rescued with addition of Ferrostatin-1." (PMID 39192032, 2024). "For example, the IDH1-vac, an IDH1 (R132H)-specific peptide vaccine, met its primary safety endpoint in a phase I trial involving 33 grade 3 and 4 IDH1(R132H)+ astrocytomas patients." (PMID 38515213, 2024). "Six specimens diagnosed as oligodendroglioma or likely oligodendroglioma were eventually diagnosed as (IDH1 mutant astrocytoma, two cases; one DNET and two pilocytic astrocytoma and a diffuse glioma)." (PMID 38764578, 2024). "The OS in our data set is slightly longer than the reported survival of IDH1/2 wt astrocytomas (23.8 months) in a cohort of 67 patients and considerably shorter than the OS of IDH1/2 wt astrocytomas WHO II (59 months)." (PMID 38326661, 2024). "T1, T1C, FLAIR, and ADC images were used to generate radio-pathomic maps of tumor characteristics for 79 pre-treatment patients with a primary GBM or high-grade IDH1-mutant astrocytoma for this study." (PMID 38372901, 2024). "Several studies have uncovered molecular mechanisms of malignant transformation in IDH1-mutant astrocytoma." (PMID 38012788, 2023). "According to the latest (2021) WHO classification, IDH-1 mutant astrocytomas have a more favorable prognosis and cannot be longer classified as GBM." (PMID 37300955, 2023). "We selected a patient with IDH1-mutant (R132H) astrocytoma to assess the prevalence of tumor cells in high-density cultures." (PMID 36632958, 2023). "In IDH1-mutant astrocytoma cases with available clinical and CNA data (total 161 cases), we found that tumors harboring either CDKN2A deletion, PDGFRA amplification, CDK4 amplification, or MDM2 amplification conferred poor prognosis in these cohorts." (PMID 38012788, 2023). "We also found that xenograft formation was correlated with poor prognosis in IDH1-mutant astrocytoma patients." (PMID 38012788, 2023).
astrocytomas (continued). "In a clinical trial (NCT02454634) evaluating the IDH1-specific vaccine in patients with IDH1(R132H) + astrocytoma, vaccine-related side effects were limited to grade 1, and no significant toxicity that would impact the treatment regimen was observed." (PMID 37681891, 2023). "Intriguingly, within the lipid deposits of IDH1 mutant (IDH1-mt) astrocytoma tumor cells, our study identified extranuclear DNA (enDNA) fragments." (PMID 38168422, 2023). "Diffuse infiltrating low-grade glioma (LGG) is classified as WHO grade 2 astrocytoma with isocitrate dehydrogenase (IDH) mutation and oligodendroglioma with IDH1 mutation and 1p/19q codeletion." (PMID 36765553, 2023). "To verify if IDH1/2-mutant astrocytomas with CDKN2A, PDGFRA, CDK4, or MDM2 CNA promotes poor prognosis, we used the GLASS and MSK diffuse glioma datasets (total 1,448 cases)." (PMID 38012788, 2023). "Here, using RNA-seq data from our GBM tissue samples and excluding astrocytoma grade 4 IDH-1 mutant tumors, we found lower expression levels of Gal-1 in the proneural molecular subtype, validating the virtual analysis performed with public databases." (PMID 36980184, 2023). "Mutations in IDH1 or IDH2 are disease-defining features of IDH-mutant and 1p/19q co-deleted oligodendroglioma and IDH-mutant astrocytoma." (PMID 37919784, 2023). "According to these results, all samples were characterized as adult-type diffuse gliomas; BT32 and BT39 samples bear an IDH1 R132H mutant allele and correspond to grade III astrocytoma, respectively." (PMID 36835465, 2023). "This astrocytoma (WHO grade 2) presented IDH1-wt in IHC while direct sequencing was shown as IDH1-R132H." (PMID 37029174, 2023). "For instance, we have demonstrated that additional “tertiary mutations”, such as PDGFRA and MYCN amplification, promoted patient tumor progression and xenograft formation in IDH1-mutant astrocytoma." (PMID 38012788, 2023). "While WHO grade 2–3 astrocytomas with IDH1-mut and IDH1-wt LGGs required the maximum safe resection beyond the abnormal range shown by MRI, even several milliliter tumor residues can bring a poor prognosis." (PMID 37029174, 2023). "Histopathological examination supplemented with immunoreaction to IDH1 R132H showed an increased presence of IDH-mutant astrocytomas." (PMID 36136867, 2022). "An IDH1 inhibitor for Grade 3 (n = 1) IDH-mt astrocytoma and FGFR inhibitors and pembrolizumab for diffuse midline glioma (n = 1) were recommended." (PMID 35626060, 2022). "IDH1-vac safely targets IDH1R132H in newly diagnosed astrocytomas with transient or sustained immune responses in 93.3% of treated patients." (PMID 35599302, 2022). "In a single-arm, multicenter, open-label Phase I trial performed in patients with newly diagnosed Grade 3 and 4 IDH1-mutant astrocytoma, an IDH1-specific peptide vaccine induced an immune response in 30 out of 32 (93.3%) patients." (PMID 35406398, 2022). "The study population included 104 adult patients with a histologically confirmed supratentorial WHO grade 2 astrocytoma (IDH1/2 mutant, ATRX mutant, n = 70) or oligodendroglioma (IDH1/2 mutant, 1p19q codeleted, n = 34)." (PMID 35356212, 2022). "IDH-mutant astrocytoma IDH-mutant is a diffuse astrocytic glioma, presenting mutations in IDH1 or, less frequently, IDH2 genes." (PMID 36553127, 2022). "After stratifying the cases according to the IDH1 gene, we noticed that the impact of altering the CDKN2A gene, associated with mortality, was higher in the case of IDH-mutant astrocytomas (p = 0.002)." (PMID 36136867, 2022). "Here, we describe a case of a concurrent IDH1 and IDH2 mutations in a patient with a CNS WHO grade 3 astrocytoma, with prolonged time to recurrence." (PMID 36286062, 2022).
astrocytomas (continued). "These included an IDH2 R172K alteration detected in an oligodendroglioma, as well as IDH1 R132G (1 case) and IDH1 R132S (2 cases) mutations, all three of which were seen in IDH-mutant infiltrating astrocytomas." (PMID 36397144, 2022). "In a phase I trial, 32 patients with IDH1 (R132H)+ astrocytomas were given an IDH1(R132H)-specific peptide vaccination and the vaccine-induced immune responses were observed in 93.3% of individuals, with vaccine-related adverse effects limited to grade 1." (PMID 35874694, 2022). "A multicentre, single-arm, open-label, first-in-humans phase I trial was carried out in 33 patients with newly diagnosed WHO grade 3 and 4 IDH1 (R132H)+ astrocytomas (NCT02454634)." (PMID 36361831, 2022). "Mutations in IDH1 and IDH2 have been frequently observed in astrocytoma and oligodendroglioma patients." (PMID 36347915, 2022). "Our group has previously reported a correlation between increased LOX expression and higher malignancy grade in human astrocytomas, and also a correlation of LOX expression with IDH1 mutation status." (PMID 36076905, 2022). "Accordingly, the cohort consisted of three IDH1 mutant glioblastomas (astrocytoma grade 4) and 34 IDH wild-type glioblastomas." (PMID 35419292, 2022). "In IDH1-mut versus IDH1-WT astrocytoma WHO grades II/III (comparison II), only 3 pathways were significantly (P < 0.05) altered." (PMID 34941573, 2022). "b ROC curve of FMISO PET for differentiating IDH1-wildtype tumors from IDH1-mutant tumors in malignant astrocytomas (n = 76; 18 AAs and 58 GBMs)." (PMID 34291337, 2021). "According to the more detailed histological classification, oligodendroglioma (23 cases), astrocytoma (14 cases), oligoastrocytoma (17 cases), IDH1 mutant (33 cases), and IDH1 wild type (67 cases) were identified." (PMID 35111665, 2021). "Considering that IDH1 wild-type GBMs are developed from IDH1 wild-type grade II or III astrocytomas or as de novo, which are originally different from IDH1-mutant astrocytomas and oligodendrogliomas or 1p19q codeleted oligodendrogliomas." (PMID 34722888, 2021). "Isocitrate dehydrogenase (IDH) is another TCA cycle enzyme that converts isocitrate to alpha-ketoglutarate, and IDH1/IDH2 mutations have been reported in a number of cancers including leukemia, melanomas, oligodendrogliomas, and astrocytomas." (PMID 33804114, 2021). "In multivariate analysis, after adjusting for IDH1 mutation, tumour grade, gender and age, YAP1 levels were an independent prognostic factor for chemotherapy-treated recurrent astrocytoma (HR (95% CI): 4.06 (1.32–12.27), p = 0.013)." (PMID 34771529, 2021). "We find that cystathionine-γ-lyase (CSE), the enzyme responsible for cysteine production upstream of GSH biosynthesis, is specifically upregulated in IDH1-mutant astrocytomas." (PMID 34250481, 2021). "In grade II IDH1 mutant astrocytoma, cg07425555 and cg24354933 were significant prognostic factors for OS." (PMID 34830454, 2021). "We compared STOX1 expression of IDH1 wild-type GBMs with IDH1 wild-type astrocytomas and IDH1-mutant GBMs with IDH1-mutant astrocytomas." (PMID 34722888, 2021). "All cases harbored IDH1 mutations, 90% of which were IDH1-R132H similar to conventional supratentorial IDH-mutant astrocytomas." (PMID 33216206, 2021). "The results revealed that STOX1 expression in IDH1 wild-type GBMs was significantly lower than that of IDH1 wild-type astrocytomas in both datasets (Figure A1a and b)." (PMID 34722888, 2021).
astrocytomas (continued). "One patient (man) had IDH1 wild-type astrocytoma grade II with radiological necrosis, while 15 patients (10 women) had IDH1 wild-type astrocytoma grade III with radiological necrosis." (PMID 33742279, 2021). "For astrocytoma patients, we show this difference has clinical relevance as patients harbouring such non-IDH1R132H IDH1/2-mutated tumours have improved survival compared to those harbouring IDH1R132H mutations." (PMID 33740099, 2021). "There were three cases of oligodendroglioma, seven cases of astrocytoma, 11 cases of oligoastrocytoma, four cases of IDH1 mutant type, and 16 cases of IDH1 wild type." (PMID 35111665, 2021). "Our analysis of mRNA expression levels showed that two genes that promote cell proliferation and invasion, DRG2 and MSN, were under-expressed in IDH1-mutant astrocytoma compared to normal tissue and IDH1-wildtype patients." (PMID 34503108, 2021). "Our analysis identified signature genetic changes in IDH1-mutant and -wildtype astrocytoma that aid in understanding the differences in overall survival and prognosis of these cancers." (PMID 34503108, 2021). "The histo-pathological examination revealed an astrocytoma WHO II, IDH1 mutated, and the patient was treated with proton radiation therapy and adjuvant chemotherapy with temozolomide." (PMID 33584207, 2020). "75% of grade II–III astrocytomas and secondary GBM harbor ATRX abberations linking IDH1 mutations with ATRX and ALT." (PMID 31960234, 2020). "Several studies point towards an evolution of diffuse gliomas upon treatment and recurrence, where IDH1/2mut astrocytomas show most and IDHwt GBMs least changes in relapsed tumors." (PMID 33009951, 2020). "To overcome this limitation, we conducted a 72 h treatment for mutant IDH1-R132H BT142 (astrocytoma) and TS603 (oligodendroglioma) cell lines with AGI5198, which specifically inhibits IDH1R132H enzyme activity disrupting D-2HG formation." (PMID 33050528, 2020). "Patients with IDH1-mutant astrocytomas have a better overall prognosis compared with those with IDH1-wildtype astrocytomas, even after controlling for histologic grade." (PMID 32382870, 2020). "IDH1 R132 mutation is reported to occur in 55-80% of grades II and III oligodendrogliomas and astrocytomas." (PMID 32856857, 2020). "Expression of IDH1 R132H assessed by IF in the astrocytomas was too weak to perform reliable double pSTAT3/IDH1 R132H stainings so, as an alternative, pSTAT3/ATRX stainings were done." (PMID 32218467, 2020). "IDH1R132H immunoreactivity in tumor cell components occurred in most WHO II astrocytoma, and sanger sequencing revealed 68.7% (79/115) of WHO II astrocytoma occurred IDH1/2 mutated in our cohorts." (PMID 32047544, 2020). "In adults, depending on grade and tumor subtype (e.g., oligodendroglioma vs. astrocytoma, IDH1-mutant vs. IDH1-wild-type) survival can range from a months to over a decade." (PMID 32508561, 2020). "Here, we present two siblings with IDH1 R132H mutant high grade astrocytomas diagnosed at 14 and 26 years of age." (PMID 32010615, 2020).